EIF2B4 (eukaryotic translation initiation factor 2B subunit delta)
Description:
Acts as a component of the translation initiation factor 2B (eIF2B) complex, which catalyzes the exchange of GDP for GTP on eukaryotic initiation factor 2 (eIF2) gamma subunit. Its guanine nucleotide exchange factor activity is repressed when bound to eIF2 complex phosphorylated on the alpha subunit, thereby limiting the amount of methionyl-initiator methionine tRNA available to the ribosome and consequently global translation is repressed.
Synonyms: EIF2Bdelta; EIF-2B; DKFZP586J0119; EIF2B; VWM4
Tractability: Small molecule: a structure with a bound ligand is known. PROTAC: ubiquitination databases record sites on it; its protein half-life has been measured.
Gene: Protein-coding gene on chromosome 2 (27,363,420 to 27,370,400, reverse strand). Ensembl gene ENSG00000115211.
Subcellular location: Cytoplasm, cytosol
Subcellular location (Human Protein Atlas): Endoplasmic reticulum
Pathways (Reactome):
Metabolism of proteins: Recycling of eIF2:GDP
Gene Ontology:
Molecular function: guanyl-nucleotide exchange factor activity; protein binding; translation initiation factor activity; translation initiation factor binding
Biological process: cytoplasmic translational initiation; myelination; oligodendrocyte development; ovarian follicle development; positive regulation of translational initiation; T cell receptor signaling pathway; translational initiation; regulation of translation; response to glucose; response to heat; response to peptide hormone; animal organ development; central nervous system development
Cellular component: cytoplasm; eukaryotic translation initiation factor 2B complex; cytosol
Genetic constraint (gnomAD): Loss-of-function variants: 34 observed, 65.9 expected, observed/expected ratio (o/e) 0.52, 90% interval 0.39 to 0.69. The upper end of that interval is the gene's LOEUF score, 0.69, which puts it in group 2 of 6, group 1 being the genes least tolerant of losing a copy. Missense variants: 618 observed, 665.71 expected, observed/expected ratio (o/e) 0.93, 90% interval 0.87 to 0.99. Synonymous variants: 278 observed, 258.44 expected, observed/expected ratio (o/e) 1.08, 90% interval 0.97 to 1.19.
Gene-disease validity (ClinGen):
ClinGen rates the evidence that EIF2B4 causes each of these diseases.
leukoencephalopathy with vanishing white matter 4 (autosomal recessive): Definitive.
Homologues: Orthologues: chimpanzee EIF2B4 (99% identical), macaque EIF2B4 (99% identical), dog EIF2B4 (91% identical), pig EIF2B4 (90% identical), guinea pig EIF2B4 (88% identical), mouse Eif2b4 (86% identical), rat Eif2b4 (86% identical), rabbit EIF2B4 (84% identical), tropical clawed frog eif2b4 (63% identical), zebrafish eif2b4 (62% identical), Drosophila melanogaster eIF2Bdelta (39% identical), Caenorhabditis elegans eif-2Bdelta (21% identical). Paralogues in human: MRI1 (17% identical), EIF2B2 (15% identical), EIF2B1 (15% identical).
Diseases named in the same sentence as EIF2B4 in open-access papers:
EIF2B4 is named in the same sentence as 24 diseases in open-access papers, as found by Europe PMC text mining. Sharing a sentence is not in itself a finding about the gene and the disease. The quoted sentences say what the papers report.
ovarioleukodystrophy (4 papers, 2021 to 2024). The "ovarioleukodystrophies" comprise a group of rare leukodystrophies associated with primary or premature ovarian failure. "The majority of mutations reported to contribute to VWM or ovarioleukodystrophy (OLD) are missense mutations in the EIF2B4 gene, but this mutation has not been reported in the HGMD and ClinVar databases." (PMID 35860328, 2022).
hepatocellular carcinoma (1 paper, 2025). A malignant tumor that arises from hepatocytes. "Our findings hold significant translational implications: A predictive model integrating EIF2B4 expression levels with TMB and PD-L1 status may optimize treatment stratification for hepatocellular carcinoma patients receiving immune checkpoint therapy." (PMID 41144132, 2025).
hyperinsulinism (1 paper, 2019). Abnormally high levels of insulin in the blood. "Both patients had compound heterozygous pathogenic variants in EIF2B4 detected on exome sequencing and absence of other variants which might explain the hyperinsulinism." (PMID 32071834, 2019).
premature ovarian failure (1 paper, 2020). "The c.1117C > T (p.Arg373Cys) variant in EIF2B4 was shown to be associated with premature ovarian failure in two patients at the ages of 13 and 18 years, respectively." (PMID 32962729, 2020).
cancer (6 papers, 2023 to 2025). A tumor composed of atypical neoplastic, often pleomorphic cells that invade other tissues. "All components, except EIF2B4, are also overexpressed in HNSCC, often showing a progression with cancer stage and grade." (PMID 38001610, 2023). "The function of CYP2C9, DPH2, EIF2B4, and HEXB on cancer remains unclear, and their biological effects and clinical significance wait for further research in HCC." (PMID 39041652, 2024). "Here, several growth-associated genes were up-regulated, including RNA helicase (HELLS), PRR11, CDCA8, and DNA topoisomerase 2 (TOP2A), HMGB2, EIF2B4, and CDKN3, which are thought to serve important functions during growth stimulation, many of which are known to be up-regulated in various cancers." (PMID 37907238, 2024).
tumor (4 papers, 2021 to 2025). "GEF-inactivating mutations abolished EIF2B4’s translational and tumor-promoting effects." (PMID 41144132, 2025). "In addition, EIF2B4 impairs antitumor immunity by reducing tumor susceptibility to CD8+ T cell-mediated cytotoxicity." (PMID 41144132, 2025). "This weight divergence likely reflects differential tumor burden or treatment tolerance conferred by Eif2b4 KO." (PMID 41144132, 2025). "This work positions EIF2B4 as a master regulator of tumor-immune crosstalk and a promising therapeutic target for combination immunotherapy." (PMID 41144132, 2025). "In contrast, the tumor-specific role of EIF2B4, the catalytic subunit of the eIF2B complex, remained unexplored." (PMID 41144132, 2025). "The functional enrichment analyses preliminarily revealed that EIF2B4 promotes tumor progression through translational regulation and cell cycle control." (PMID 41144132, 2025). "The tumor-promoting effect of EIF2B4 was found to be STAT3-dependent, as STAT3 knockout completely abolished EIF2B4-driven phenotypes." (PMID 41144132, 2025). "Anti-PD-1 treatment elicited significantly stronger tumor regression in Eif2b4 KO mice compared to WT controls." (PMID 41144132, 2025). "To elucidate the mechanisms underlying EIF2B4-driven tumor proliferation, we performed transcriptomic sequencing on Hep3B cells with or without EIF2B4 knockout (KO)." (PMID 41144132, 2025). "These impaired malignant phenotypes induced by EIF2B4 loss were likely associated with a pronounced cell cycle arrest, which aligned with bioinformatic predictions that EIF2B4 fuels tumor progression by accelerating proliferation through its canonical translational role." (PMID 41144132, 2025). "Complementing this, our in vivo models reveal that EIF2B4 fosters a “cold” tumor phenotype by impeding immune cell infiltration and upregulating PD-L1 to enforce adaptive immune resistance, thereby positioning EIF2B4 as a promising therapeutic target to enhance ICB sensitivity." (PMID 41144132, 2025). "Furthermore, TMB, a hallmark of malignancy, exhibited a positive correlation with EIF2B4 levels, suggesting that EIF2B4 may exacerbate genomic instability to fuel tumor progression." (PMID 41144132, 2025). "Functional enrichment analyses further suggested that EIF2B4 may drive HCC progression via dual mechanisms: directly accelerating tumor cell cycle progression through translation reprogramming, and shaping an immunosuppressive microenvironment via aberrant synthesis of immune-modulatory molecules." (PMID 41144132, 2025). "By integrating TCGA cohort analyses, functional experiments, and in vivo models, we provide the first clinical evidence linking elevated EIF2B4 expression to poor HCC prognosis, while mechanistically implicating its translational regulatory role in tumor progression and immune evasion." (PMID 41144132, 2025).
neurodevelopmental disorder (1 paper, 2022). A behavioral and cognitive disorder with onset during the developmental period that involves impaired or aberrant development of intellectual, motor, or social functions. "Five of these genes are already classified as diagnostic grade genes in the IEM panel (COQ4, ELAC2, MRPL44, MSTO1 and SKIV2L) and three others are diagnostic grade genes in different neurology and neurodevelopmental disorder gene panels (EIF2B4, ELP1, EXOSC8)." (PMID 36229886, 2022).
EIF2B4 also shares sentences with these, for which no sentence is quoted: Leukoencephalopathy (4 papers); Vanishing White Matter Disease (3); breast carcinoma (2); Adult onset (1); CADASIL (1); Cerebroretinal vasculopathy (1); cognitive decline (1); dementia (1); dyslipidemia (1); fibrodysplasia ossificans progressiva (1); Hyperglycemia (1); leukodystrophies (1); metachromatic leukodystrophy (1); neurological disorders (1); Obesity (1); ovarian failure (1); type 2 diabetes (1).